LINC01962 (long independently transcribed non-coding RNA 1962)
Gene: Long non-coding RNA gene on chromosome 5 (181,178,821 to 181,191,956, reverse strand). Ensembl gene ENSG00000248473.
Gene Ontology:
Molecular function: triplet codon-amino acid adaptor activity
Biological process: translation